MMP2 (matrix metallopeptidase 2)
Diseases named in the same sentence as MMP2 in open-access papers (continued):
Sharing a sentence is not in itself a finding about the gene and the disease.
renal fibrosis (78 papers, 2010 to 2025). A final common manifestation of a wide variety of chronic kidney diseases characterized by glomerulosclerosis and tubulointerstitial fibrosis. "MMP9 and MMP2 belong to the matrix metalloproteinase family and are closely associated with the process of hypertensive nephropathy and renal fibrosis." (PMID 40391375, 2025). "Elevated levels of MMP2 and 9 have been associated with renal fibrosis in CKD." (PMID 33782857, 2022). "Moreover, a systematic review showed that MMP-2 has the potential to identify patients at risk of renal fibrosis that leads to worse renal outcomes." (PMID 34992536, 2021). "Our result also indicates the importance of MMP2 in age-associated renal fibrosis." (PMID 29464020, 2018). "Nonetheless we can conclude from the published data that TGF-β, MCP-1 and MMP-2 may identify patients at risk for renal fibrosis and hence worse renal outcomes." (PMID 28219345, 2017). "In addition, it has been shown that reduced expression of MMP9 in the cytoplasm of normal tubular cells is associated with renal fibrosis, whereas MMP2 is associated with structural changes in the tubular basement membrane leading to tubular atrophy and fibrosis." (PMID 35045102, 2022). "For instance, Research indicates that HE4 activates the NF-κB pathway by promoting C3 and MMP2/9 expression, driving renal fibrosis." (PMID 41502510, 2025). "Periostin and matrix metalloproteinase-2 (MMP-2) were selected to evaluate the effect of irisin on renal fibrosis in UUO mice." (PMID 38870184, 2024). "At the early stage of renal fibrosis, MMP2 facilitates degradation of the glomerular baseline membrane and destroys the filtration barrier, which accelerates CKD progression." (PMID 37266145, 2023). "Specifically, matrix metalloproteinases (MMPs), a family of zinc-containing endopeptidases, such as MMP2 and MMP9 have been linked to alterations of the tubular basement membrane, leading to renal fibrosis and tubular atrophy." (PMID 35045102, 2022). "In fact, there is another molecule in humans, EMMPRIN (or CD147), which has a significant impact on both the regulation of MMP-2 activation and the development of renal fibrosis." (PMID 36185410, 2022). "CD147 can not only directly promote the development of kidney fibrosis but also differentially regulate MMP-2 activity at different stages of renal fibrosis." (PMID 36185410, 2022). "In contrast, BDKRB2 activation protected against renal fibrosis via the PA/MMP-2 cascade by increasing ECM degradation." (PMID 34830489, 2021). "Since the increase in MMP-9 activity was more striking than that of MMP-2 in our present study, it was thus plausible that MMP-9 was more predominant than MMP-2 in driving renal fibrosis mediated by COM-MP secretome." (PMID 34381146, 2021). "Accordingly, Cheng and colleagues showed that MMP-2 overexpression in the kidney is sufficient to generate all the phases of renal fibrosis via pathways involving TGF-β signaling, EMT, and collagen type IV degradation." (PMID 33573220, 2021). "Since MMP-2 is a target gene of STAT3, JAK2/STAT3 blockade reduced MMP-2 expression and renal fibrosis in the developing kidney with obstruction." (PMID 31846485, 2019). "Hypoxia plays an important role in the pathogenesis of renal fibrosis and MMP-2 activation mainly occurs on the surface of the cell membrane." (PMID 29462885, 2018). "Considering this, the decrease in MMP2 activity by cGMP/cGKI can ameliorate the progression of renal fibrosis." (PMID 28396839, 2017). "In several animal models of renal fibrosis, early increases in MMP-2, TIMP-1 and TIMP-3 expression and activity have been observed, suggesting accelerated ECM turnover following injury." (PMID 27455234, 2016). "MMP-2 deletion and minocycline treatment in mouse obstructive nephropathy showed amelioration of renal fibrosis via inhibition of EMT and macrophage infiltration." (PMID 27455234, 2016).
renal fibrosis (continued). "The effect of pharmacological inhibition of Mmp2 seems to be dependent on the time of administration in UUO-induced renal fibrosis." (PMID 26673451, 2015). "Important roles in extracellular matrix remodeling belong to metalloproteinases, especially MMP-2 and -9 which are able to degrade collagen, essential component of normal kidney interstitium but abundantly accumulated in renal fibrosis." (PMID 26327314, 2015). "Matrix Metalloproteinase-2 (Mmp2) is a collagenase known to be important in the development of renal fibrosis." (PMID 26673451, 2015). "Overexpression of MMP-2 in transgenic mice promotes renal fibrosis and generates the entire spectrum of pathological and functional changed characteristics mimicking human CKD." (PMID 23922934, 2013). "MMP-2/9, in particular MMP-2, have pivotal roles in initiating renal fibrosis by degrading TBM components and disrupting its integrity." (PMID 20441599, 2010). "MMP-2 and MMP-9 play various roles in the renal disease progression, contributing to loss of glomerular cell junctions, epithelial-to-mesenchymal transition, and increased renal fibrosis, accelerating the decline in renal function." (PMID 39123230, 2024). "Matrix metalloproteinase-2(MMP2) play an important role in renal fibrosis and DN." (PMID 36896170, 2023). "However, during renal fibrosis, the expression of MMP2 and 9 is rapidly upregulated due to abnormal activation and interaction of multiple cell signaling pathways." (PMID 37553369, 2023). "MMP-2 aggravates the expression of EMT-associated molecules and renal fibrosis in adult UUO." (PMID 38015955, 2023). "There have been few studies on the specific pathway by which CD147 regulates MMP-2 activity in renal fibrosis; nonetheless, by combining the results of earlier studies by our group and others, we propose one possible regulatory pathway in the advanced stage of kidney fibrosis." (PMID 36185410, 2022). "The upregulation of caveolin-1 expression affects the hyperglycosylation of CD147, leading to insufficient MMP-2 activation; in addition, the hypoxic conditions in renal fibrosis evoke intense endocytic activity, which drastically alters the structure of the cell membrane." (PMID 36185410, 2022). "However, more evidence is still needed to determine the role of MMP-2 in evaluating the progression of renal fibrosis in CKD." (PMID 34992536, 2021). "Indeed, the expression of MMP2 and 9 has been positively correlated with renal fibrosis in recent studies." (PMID 34127702, 2021). "In the future, Rab7 may be a therapeutic target for renal fibrosis, if the balance between the expression of Rab7 and autophagic activity and the expression of MMP-2 can be found in the course of the disease." (PMID 32267310, 2020). "The role of MMP-2 in renal fibrosis was shown in several experimental studies." (PMID 32670438, 2020). "The contribution of MMP-9 in renal fibrosis was evaluated more extensively than MMP-2." (PMID 32670438, 2020). "Reduced MMP-2 expression during UUO protects mice against renal fibrosis." (PMID 31846485, 2019). "In support, MMP-2 has been shown to induce complex alterations characterizing renal tubular epithelial-mesenchymal transformation leading to increased renal fibrosis, which could lead to decreased renal function." (PMID 28446168, 2017). "However during the process of renal fibrosis, the mRNA transcription levels of MMP-2 and 9 are upregulated rapidly due to the abnormal activation and interactions of multiple cell signaling pathways." (PMID 28397744, 2017). "MMP-2 has a role in renal fibrosis, particularly during the early pre-fibrotic stage." (PMID 23144821, 2012). "MMP-2 has a role in renal fibrosis, especially during early pre-fibrotic stage." (PMID 20441599, 2010). "Interestingly, the CXCL8 antagonist G31P has been shown to improve renal fibrosis by reducing ECM, which may be associated with improved expression of MMP-2 and MMP-9." (PMID 37287620, 2023).
renal fibrosis (continued). "Therefore, MMP2 appears to be more crucial in the development of renal fibrosis than MMP9." (PMID 28396839, 2017). "Emerging evidence implicates HE4 in fibrotic pathogenesis: In renal fibrosis, it drives pathological ECM accumulation via protease inhibition, specifically by blocking MMP-2 activity." (PMID 41502510, 2025). "Their findings demonstrated that these gold NPs exhibited nephroprotective effects, including the attenuation of renal fibrosis, as evidenced by reduced levels of transforming growth factor-beta 1 (TGF-β1) and matrix metalloproteinase-2 (MMP-2)." (PMID 40427546, 2025). "Several studies have shown that ROS accumulation promotes the expression of MMP2, and MMP9 participates in all stages of different forms of CKD, which is characterized by renal fibrosis." (PMID 38785272, 2024). "To explore potential mechanisms of renal fibrosis, we measured the content of key renal fibrotic markers (TGF-β, TIMP, and MMP-2/9) using real-time PCR." (PMID 38655071, 2024). "The results show that the coadministration of SCG or VAL inhibited renal fibrosis in hyperuricemic rats by suppressing the TGF-β1/Smad2/3 pathway and decreasing MMP2 production to reduce ECM formation." (PMID 37446016, 2023). "After 6 months, the treated group showed increased levels of MMP-2 and MMP-9, reduced levels of TIMP-1, TIMP-2, and TGF-β/Smad signalling, improved renal fibrosis and enhanced renal function." (PMID 37196129, 2023). "The administration of the MCs membrane stabilizer, sodium cromoglycate (SCG), decreased the expression of SCF/c-kit, reduced the expression of α-SMA, MMP2, and inhibited the TGF-β1/Smad2/3 pathway, thereby alleviating renal fibrosis." (PMID 37446016, 2023). "TGF-β1 and MMP2/9 are essential factors in renal fibrosis, which promotes excessive deposition of extracellular matrix (ECM) and promotes renal fibrosis." (PMID 37446016, 2023). "The renal fibrosis amelioration was confirmed by the reduction in mRNA levels of Acta2, Collagen I, Collagen III, Mmp2, and Mmp9 and the protein levels of ACTA2, fibronectin, and Collagen I in UI30/2wk Pfkfb3f/f/PostnMCM kidneys compared to PostnMCM kidneys." (PMID 37626891, 2023). "Elevated HE4 inhibits the degradation of collagen I by inhibiting the activity of serine proteases (Prss23 and Prss35) and matrix metalloproteinases (MMP-2 and MMP-9) and accelerates the deposition of type I collagen in the kidneys, leading to renal fibrosis." (PMID 37753112, 2023). "Oxidative stress exacerbates glomerular endothelial cell and tubular epithelial cell damage and increases the expression of inflammatory mediators such as PAI-1, MMP-2 and TGF-β, leading to the development of renal fibrosis." (PMID 37429602, 2023). "Our data are in line with other research that identified CHR-mediated inhibition of pro-fibrotic pathways in rat myocardial injury, renal fibrosis and osteoarthritis, by reducing TGF-β1/Smad3, p38, Erk1/2, MMP2 and PERK/TXNIP/NLRP3 signalling." (PMID 38169923, 2023). "In renal fibrosis, potential renal fibrosis biomarkers include TGF-β, monocyte chemoattractant protein-1 (MCP-1) and MMP-2, or urinary excretion of collagen III and related proteins such as the N-terminal pro-peptide of type III collagen." (PMID 37814303, 2023). "Accordingly, the change in membrane structure can also affect CD147 function, thereby negatively impacting MMP-2 activation and thus reducing ECM degradation in the advanced stage of renal fibrosis." (PMID 36185410, 2022). "The implication of MMP2 and MMP9 in renal fibrosis is controversial as their expression/activity was reported to be both up- and downregulated depending on the stage of CKD." (PMID 34127702, 2021). "It was previously reported that ECM alleviation was mediated mainly by MMPs, including matrilysins and collagenases, etc, especially MMP2 and MMP9, which are closely correlated with renal fibrosis." (PMID 33507617, 2021).
renal fibrosis (continued). "The ECM degradation is mainly catalysed by MMPs, including MMP2 and MMP9, which are related to renal fibrosis." (PMID 33507617, 2021). "In tissues from cats with CKD, transcript abundance of MMP2 and MMP7 was correlated with worsening degrees of renal fibrosis." (PMID 32468592, 2020). "Matrix metalloproteinase-2 (MMP-2) is a 72 kDa collagenase that is important in extracellular matrix metabolism and renal fibrosis." (PMID 31846485, 2019). "The current study showed that exercise training suppressed TGF-β, p-Smad2/3, CTGF, MMP2, and MMP9 expression to decrease renal fibrosis." (PMID 29461477, 2018). "The COL4A3−/−/ITGA2−/− double knockout Alport mouse model has delayed renal fibrosis compared with COL4A3−/−/ITGA2+/+ Alport mice, which express significantly higher levels of MMP2, MMP9, MMP12, and TIMP155." (PMID 29196624, 2017). "In conclusion, reduced Mmp2 expression during UUO protects mice against hydronephrosis and renal fibrosis." (PMID 26673451, 2015). "Our previous studies showed that Sal B had anti-oxidant effects, and in this study, we found that Sal B can also inhibit MMP-2 activity in the diseased kidney and subsequently protect tubular basement membrane and prevent EMT and renal fibrosis." (PMID 20441599, 2010). "Celastrol treatment improved renal fibrosis by decreasing TGF-β1 and MMP-2 renal expression." (PMID 39702603, 2024). "To investigate whether SiNPs induce renal fibrosis, we determined the expression levels of MMP-9, MMP-2, TIMP-2, and TGF-β1 in kidney tissue using RT-qPCR." (PMID 38655071, 2024). "However, in the late stage, the MMP2 activity is inhibited and ECM degradation decreases, promoting renal fibrosis." (PMID 37266145, 2023). "In addition, it downregulated the expression of major fibrotic signaling factors, such as α-SMA, collagen I, MMP-2, and TIMP-1, and significantly regulated the TGF-β1/Smad pathway, which is known as a major regulator of renal fibrosis." (PMID 35572722, 2022). "Potential biomarkers of renal fibrosis include TGF-β and matrix metalloproteinase 2 (MMP-2)." (PMID 35698028, 2022). "Based on these findings, we speculate that inhibition of autophagy with 3-MA may decrease collagen formation and ECM protein deposition through regulating the activity of MMP2/MMP9, which results in alleviating hyperuricemic-related renal fibrosis." (PMID 32555189, 2020). "Monitoring of urinary and serum MMP-2, -9 and MMP-2, -9/TIMP-1, -2 ratios may become useful in determining the progression of renal fibrosis and better stratification of patients with ON." (PMID 32670438, 2020). "It is also speculated that MCP-1 and MMP-2 contribute to progressive fibrosis, whereas IFN-γ is considered to be an antifibrotic cytokine that attenuates renal fibrosis." (PMID 33344483, 2020). "And increased MMP-2 activity can in turn promote ECM degradation, which also contributes to the reversal of renal interstitial fibrosis Therefore, this study further supports the viewpoint that Src is a promising target for the treatment of renal fibrosis." (PMID 29462885, 2018). "In this study, we show that the pan-DUB inhibitor PR-619 reduces expression of mesenchymal markers, deposition of ECM proteins, expression of MMP2 and MMP9, the degree of apoptosis, macrophage infiltration, and the TGF-β1 mRNA level, and attenuates renal fibrosis." (PMID 30114247, 2018). "SalB also reduces the expressions of inflammatory factors, such as interleukins (IL-1β, IL-6, and IL-8), alleviates apoptosis of vascular cells to improve heart function, reduces liver and renal fibrosis via down-regulating transforming growth factor β1 (TGF-β1) and depressing MMP-2 activity." (PMID 27893819, 2016). "A recent study showed that binding of HE4 to MMP2 and MMP9 in renal cells promotes renal fibrosis." (PMID 25362534, 2014). "It is suggested by the results that abnormal expressions of MMP-2 and TIMP-1 might play roles in the development of renal fibrosis in chronic AMR." (PMID 23057632, 2012).
renal fibrosis (continued). "Snail1 and Twist1, two markers of EMT, and MMP2, a marker of invasion and migration, which could degrade the extracellular matrix, were downregulated in TRIM6 knockdown CRC cells, which is consistent with a study on TRIM6 in renal fibrosis." (PMID 34589421, 2021). "However, MMP-2 and MMP-9 also play a role in the process of renal fibrosis." (PMID 34205319, 2021). "Furthermore, MMP-2 and MMP-9 directly affect renal tubular cells, especially by impairing the cell-to-cell adhesion, leading to epithelial-to-mesenchymal transition (EMT), which contributes to renal fibrosis." (PMID 34402375, 2021). "Indeed, DCN increases MMP-2 and MMP-9 levels, reduces extracellular matrix deposition, and attenuates fibrotic changes in animal models of many pathological conditions, including proliferative vitreoretinopathy, renal fibrosis, and spinal cord injury." (PMID 33918979, 2021). "Thus, we speculated that MMP2 and MMP9 play a role in the formation of polycystic kidney lesions and renal fibrosis in a different way from MMP1." (PMID 24595031, 2014). "IMN is often accompanied by renal fibrosis, and we found that the expression of MMP-14 increased significantly in IMN, but no obvious changes were found in MMP-2 and MMP-9." (PMID 34819020, 2021).